CANX (calnexin)
Diseases named in the same sentence as CANX in open-access papers (continued):
Sharing a sentence is not in itself a finding about the gene and the disease.
gastric cancer (4 papers, 2021 to 2024). A primary or metastatic malignant neoplasm involving the stomach. "F nucleatum-induced neutrophil transcriptional activation may be implicated in gastric cancer via several candidate genes including DNAJB1, EHD1, IER2, CANX, and PH4B among the top genes of interest." (PMID 36033825, 2022). "F nucleatum-induced neutrophil transcriptional activation may be implicated in gastric cancer via several candidate genes including DNAJB1, EHD1, IER2, CANX, and PH4B." (PMID 36033825, 2022).
Obesity (4 papers, 2014 to 2024). Accumulation of substantial excess body fat. "In some studies, the overexpression of Gpnmb improved hepatic steatosis and fibrosis in a diet-induced obesity model, and that Gpnmb interacts with calnexin in liver macrophages, leading to a reduction in oxidative stress." (PMID 39040415, 2024). "In immune response module we found a highly connected molecule Calnexin which is an important molecule found in obesity." (PMID 25231063, 2014).
Alzheimer disease (3 papers, 2018 to 2020). A progressive, neurodegenerative disease characterized by loss of function and death of nerve cells in several areas of the brain leading to loss of cognitive function such as memory and language. "Other studies suggested that overexpression of ER chaperones such as BiP/Grp78 and calnexin leads to reduction of β-amyloid peptide, which is involved in the pathogenesis of Alzheimer's disease in vitro." (PMID 30154245, 2018).
experimental autoimmune encephalomyelitis (3 papers, 2021 to 2024). An autoimmune demyelinating disease of the central nervous system that is produced experimentally in animals by the injection of homogenized brain or spinal cord in Freund's adjuvant. "We previously showed that the loss of either Fabp5 or calnexin causes resistance to the induction of experimental autoimmune encephalomyelitis (EAE) in mice, an animal model of multiple sclerosis (MS)." (PMID 39273210, 2024). "Remarkably, both calnexin-deficient and Fabp5-deficient mice are resistant to the induction of experimental autoimmune encephalomyelitis (EAE), an animal model of CNS inflammation including multiple sclerosis (MS)." (PMID 39273210, 2024). "While whole-body calnexin deficiency leads to myelinopathy in mice, loss of calnexin also causes resistance to induction of experimental autoimmune encephalomyelitis (EAE), a model of inflammatory central nervous system demyelination, coincident with the phenotype of whole-body Fabp5 deficiency." (PMID 36766745, 2023).
hepatocellular carcinoma (3 papers, 2019 to 2022). A malignant tumor that arises from hepatocytes. "Analysis of co-localization of PRKCSH and calnexin showed that PRKCSH is primarily localized in the ER in hepatoma cells, indicating that the PRKCSH level is increased in the ER of these cells in comparison with normal liver cells." (PMID 31320625, 2019).
ovarian carcinoma (3 papers, 2015 to 2022). A malignant neoplasm originating from the surface ovarian epithelium. "To determine whether ROS influence the TME through tumor exosomal miRNAs, we treated ovarian cancer A2780 cells with or without H2O2, and purified A2780-derived exosomes characterized by positive exosomal markers CD63 and CD81, and a negative exosomal marker calnexin." (PMID 35086548, 2022).
autoimmune disease (2 papers, 2019 to 2020). A disorder resulting from loss of function or tissue destruction of an organ or multiple organs, arising from humoral or cellular immune responses of the individual to their own tissue constituents. "Another mutual pathway comprising PDIA4, APP and CANX genes is an ER dependent mechanism observed in both neurodegenerative and autoimmune diseases." (PMID 33066537, 2020).
breast tumor (2 papers, 2015 to 2019). "Previous reports indicate that Fra-1 and c-Fos colocalize with the ER marker calnexin in human breast tumor samples, and in MDA-MB231 and MCF7 breast tumor cell lines." (PMID 31275861, 2019).
cataract (2 papers, 2023 to 2024). Partial or complete opacity of the crystalline lens of one or both eyes that decreases visual acuity and eventually results in blindness. "Based on this, it was speculated that PDGFRB and CDKN1A were promoting genes, and PTEN, CANX, COL4A2, EIF2S1, and NPM1 were suppressing genes in cataract pathogenesis." (PMID 38662949, 2024).
COVID-19 (2 papers, 2022 to 2023). A disease caused by infection with severe acute respiratory syndrome coronavirus 2. "Only one of these phosphorylated peptides, SDAEEDGGTVsQEEEDRKPK, which was mapping to calnexin (CANX) S564-p, had decreased levels in the serum of COVID-19 patients (log2-FC = -0.227, p = 0.005, FDR q = 0.049)." (PMID 37739942, 2023). "Among them, we discovered that levels of phosphocalnexin (CANX S564-p) had decreased serum levels in COVID-19 patients, unlike the canonical non-phosphorylated protein." (PMID 37739942, 2023). "Interestingly, the levels of the canonical calnexin protein had no change in the serum of our group of COVID-19 patients, but it was upregulated in the SARS-CoV-2-infected cells 7 days after infection, and in lungs, white pulp of the spleen, and kidneys of patients who died of COVID-1930,31." (PMID 37739942, 2023). "EVs collected from the serum of both healthy controls and patients with COVID-19 were confirmed by transmission electron microscopy, and western blotting confirmed the expression of CD9, CD63, and flotillin-1, while calnexin and haptoglobin expressions were negative." (PMID 36451245, 2022).
Gaucher disease (2 papers, 2014 to 2022). Gaucher disease (GD) is a lysosomal storage disorder encompassing three main forms (types 1, 2 and 3), a fetal form and a variant with cardiac involvement (Gaucher disease - ophthalmoplegia - cardiovascular calcification or Gaucher-like disease). "In line with this, the reduction of the β-CG degradation rate promotes its delivery to the pro-folding calnexin pathway and increases enzymatic activity in Gaucher disease fibroblasts." (PMID 35992201, 2022). "Calnexin levels were significantly elevated in Gaucher disease fibroblasts [median 50% increase (IQR 50–100%), Mann-Whitney U-test P = 0.003] and Parkinson’s disease with GBA mutation fibroblasts [median 32% increase (IQR 12–50%), P = 0.019]." (PMID 24574503, 2014).
glioma (2 papers, 2020 to 2025). A benign or malignant brain and spinal cord tumor that arises from glial cells (astrocytes, oligodendrocytes, ependymal cells). "Survival analysis of data from the TCGA database confirmed that CANX was a risk factor for glioma prognosis." (PMID 39990231, 2025). "In this study, we present our findings demonstrating an association between CANX expression levels and the malignant grade of glioma, along with prognosis." (PMID 39990231, 2025). "Through predictive analyses, we found that calnexin (CANX) is one of the genes most closely associated with glioma progression." (PMID 39990231, 2025). "The results revealed that glioma patients with increased expression of CANX had increased IC50 values, which suggests that patients with increased expression of CANX require increased doses of TMZ to achieve successful chemotherapy intervention." (PMID 39990231, 2025). "An EdU-DNA synthesis assay demonstrated that BNIP3 overexpression induced protective autophagy in glioma cells, whereas reducing CANX expression in BNIP3-overexpressing cells adversely affected their proliferative ability." (PMID 39990231, 2025). "The results suggested that the CANX expression level was positively correlated with the MAPK score in glioma cells." (PMID 39990231, 2025). "By integrating transcriptome sequencing and single-cell analysis, we observed that CANX expression progressively increased with glioma grade and that higher CANX expression correlated with poorer prognosis." (PMID 39990231, 2025). "Western blot analysis revealed that CANX expression was generally elevated in glioma tissues." (PMID 39990231, 2025). "Additionally, we assessed CANX expression in human normal astrocytes (NHAs), glioma cell lines (T98G, U118MG, A172, and LN229 cell lines), and primary GBM cells (GBM#P3, GBM#BG5, and GBM#BG7 cells) using Western blotting and qPCR." (PMID 39990231, 2025). "Our study revealed that CANX was significantly upregulated in glioma patients." (PMID 39990231, 2025). "CANX was highly expressed in most glioma cells except U118-MG cells." (PMID 39990231, 2025). "Differential expression analysis revealed that CANX was highly expressed in most tumor types across datasets, including LGG, GBM, and complete glioma (LGGGBM)." (PMID 39990231, 2025). "The mRNA expression of CANX, HSPA1B, PSMC6, and TAP1 was high in gliomas, whereas that of KLRC2 was low." (PMID 32351547, 2020). "Notably, CANX expression was markedly higher in T98G cells, resistant to TMZ chemotherapy, than in other glioma cells." (PMID 39990231, 2025). "However, the function of CANX in glioma has not been fully characterized." (PMID 39990231, 2025).
leukaemia (2 papers, 2007 to 2025). "CEM-NKR is a variant of the leukaemia cell line CEM known to be deficient in calnexin expression." (PMID 17971213, 2007).
male infertility (2 papers, 2010 to 2015). The inability of the male to effect fertilization of an ovum after a specified period of unprotected intercourse. "We observed differential expression of a number of transcripts, such as PRM1, SPATA18, TNP1, EIF4G2, CANX, RANBP9, TCP11, which have previously been associated with male infertility." (PMID 25973848, 2015).
myocardial infarction (2 papers, 2020 to 2022). Gross necrosis of the myocardium, as a result of interruption of the blood supply to the area, as in coronary thrombosis. "miR-711 was upregulated by PPARγ post myocardial infarction and promoted endoplasmic reticulum stress-induced cardiomyocyte apoptosis by targeting calnexin." (PMID 36114541, 2022).
rheumatoid arthritis (2 papers, 2019 to 2024). A chronic, systemic autoimmune disorder characterized by inflammation in the synovial membranes and articular surfaces. "Antibodies to GRP78, GRP94, and Calnexin, an ER resident chaperone involved in protein folding, are found in the sera of SLE and rheumatoid arthritis (RA)." (PMID 30978945, 2019). "In rheumatoid arthritis (RA), antibodies to GRP78, GRP94, and Calnexin are found in patient sera." (PMID 39845962, 2024).
schizophrenia (2 papers, 2015 to 2019). A major psychotic disorder characterized by abnormalities in the perception or expression of reality. "Our results showed consistent downregulation of both N-glycan and calnexin/calreticulin pathways in shared genetic risk and an actual illness, implying their essential role in schizophrenia." (PMID 31477693, 2019).
xerostomia (2 papers, 2020 to 2023). Dryness of the mouth resulting from reduced salivary secretion. "In our opinion, decreased expression of genes encoding CANX and PDIA4, in SS sufferers with and without xerostomia compared to HS can lead to accumulation of misfolded proteins in the ER and changes in the quantity and quality of salivary proteins." (PMID 33066537, 2020). "In SS patients both with xerostomia (sicca) and without xerostomia (non-sicca), TMED10, PDIA4, CANX, APP, and TMBIM6 expression was lower than in HS." (PMID 33066537, 2020).
ZIKV infection (2 papers, 2023 to 2024). "Upon ZIKV infection, both calnexin and SEC61B were aggregated around the nuclei and co-localized with ZIKV E protein in the control cells, while SUN2 KO significantly dampened their aggregation." (PMID 38177122, 2024).
acute pancreatitis (1 paper, 2020). An acute inflammatory process that leads to necrosis of the pancreatic parenchyma. "Analysis by immunoblotting confirmed the presence of exosome marker TSG101 and the absence of calnexin in both exosomes from BICR-18 and from acute pancreatitis plasma origin." (PMID 33353210, 2020).
Arrhythmia (1 paper, 2023). Any cardiac rhythm other than the normal sinus rhythm. "CANX is involved in the development of arrhythmia through oocyte meiosis and focal expression and is considered as a potential biomarker of arrhythmia." (PMID 36840500, 2023).
asthma (1 paper, 2021). "GANAB and CANX belong to endoplasmic reticulum protein chaperones, which cooperate with CALR to regulate endoplasmic reticulum stress in osteoarthritis and asthma, respectively." (PMID 34910788, 2021).
Ataxia (1 paper, 2023). Ataxia refers to impaired coordination of voluntary muscle movement. "Calnexin-deficient mice were born with neurological disorders that included severe ataxia; however, one functional calnexin allele is sufficient to prevent this defect." (PMID 36766745, 2023). "The first study described the high early postnatal mortality of calnexin-deficient mice and surviving mice exhibited ataxia due to the substantial loss of motor nerve fibers." (PMID 36766745, 2023).
bladder cancer (1 paper, 2024). "Thus, we isolated sEV from bladder cancer cells by differential centrifugation, and they displayed sphere-like morphology, diameter ~ 100 nm, high expression of CD63, Alix, and TSG101, and low expression of the ER-associated chaperone protein calnexin." (PMID 38561669, 2024).
Charcot-Marie-Tooth disease (1 paper, 2019). An inherited degenerative disorder involving the peripheral nerves. "A previous study reported that Charcot-Marie-Tooth disease was related to the retention of a peripheral myelin protein 22 (PMP22) mutant regulated by RER1 and calnexin." (PMID 30630537, 2019).
cholesteatoma (1 paper, 2020). A pathologic process characterized by the proliferation of keratinizing squamous epithelium resulting in the accumulation of keratin and cells in the middle ear and/or mastoid. "A considerable variation was seen in expression levels between the different candidate reference genes, with mean Ct-values ranging from 17.74 for GAPDH in the mucosal biopsies from the TC in cholesteatoma patients to 27.70 for CANX in the MA from healthy controls." (PMID 32915926, 2020).
cystic fibrosis (1 paper, 2025). Autosomal recessive disorder caused by pathogenic variants in the CFTR gene (cystic fibrosis transmembrane conductance regulator), which encodes a chloride and bicarbonate channel expressed in epithelial cells, and follow the diagnosis criteria. "Influence of calnexin on the sensitivity of cystic fibrosis variants to VX-445 + VX-661." (PMID 41379933, 2025). "Influence of calnexin on the functional rescue of cystic fibrosis variants." (PMID 41379933, 2025). "Influence of calnexin on cystic fibrosis variant plasma membrane expression (PME)." (PMID 41379933, 2025).
dengue (1 paper, 2022). "The hepatitis B virus (HBV) envelope protein requires calnexin for proper folding and transport, and the production of infectious dengue virions is significantly reduced when calnexin is knockdown." (PMID 36238596, 2022).
fungal infections (1 paper, 2018). "We used Tg1807 CD4+ T cells, which recognize the pan-fungal antigen calnexin and confer protective immunity against various fungal infections." (PMID 29782541, 2018).
GNE myopathy (1 paper, 2013). "Immunofluorescence study showed that calnexin (Fig. 1b1), calreticulin (Fig. 1b3), GRP94 (Fig. 1c1), GRP78 (Fig. 1d1) were expressed in the muscle tissues of GNE myopathy patients whereas, normal control exhibited no immunoreactivity for these molecules (Fig. 1b2, b4, c2, and d2)." (PMID 23472144, 2013).
hyperekplexia (1 paper, 2025). "A similar phenomenon was previously reported for a glycine transporter 2 (GlyT2) mutation linked to hyperekplexia, where the mutant trapped WT intracellularly—a defect that was corrected by overexpressing calnexin." (PMID 40485335, 2025).
influenza (1 paper, 2022). An acute viral infection of the respiratory tract, occurring in isolated cases, in epidemics, or in pandemics; it is caused by serologically different strains of viruses (influenzaviruses) designated A, B, and C, has a 3-day incubation period, and usually lasts for 3 to 10 days. "In addition, both CANX and CALR are thought to contribute to human immunodeficiency/HIV type-1 (gp160) and influenza because of their impact on both HA and neuraminidase glycoproteins." (PMID 36149962, 2022). "Although CANX/CALR are typically considered to be ER/Golgi specific, these different viruses bud from different cellular compartments including the cell membrane (influenza, rabies, and HIV-1), nuclear envelope (HSV-1), multivesicular bodies (HBV), and ERGIC (Coronavirus)." (PMID 36149962, 2022).
laminopathies (1 paper, 2020). "The interaction between progerin and Ca2+‐regulating proteins (e.g., Sln and Calnexin) provides a molecular explanation for the multitude of metabolic phenotypes, such as muscle weakness and malfunctioning lipid turnover in laminopathies." (PMID 31833196, 2020).
Legionella infection (1 paper, 2025). "Calnexin levels detected were low in both WT ΔS Legionella infection at 2 h.p.i." (PMID 40506485, 2025).
liver cancer (1 paper, 2023). An epithelial or non-epithelial malignant neoplasm that arises from the liver. "All four human liver cancer cell lines were positively stained for the hepatocyte-specific markers Calnexin and HNF4alpha, while other markers were differently expressed among each other." (PMID 38201286, 2023).
liver fibrosis (1 paper, 2015). "Thus, we hypothesized that the transgenic expression of Gpnmb in Kupffer and stellate cells in liver exerts anti-oxidative actions by binding calnexin in ER and ameliorates the liver fibrosis." (PMID 26581806, 2015).
lung adenocarcinoma (1 paper, 2015). A carcinoma that arises from the lung and is characterized by the presence of malignant glandular epithelial cells. "Increased in Chop and Calnexin expressions, following loss of VCP in lung adenocarcinoma cells, were also confirmed by immunofluorescence staining." (PMID 25970786, 2015).
lupus nephritis (1 paper, 2016). Glomerulonephritis in the context of systemic lupus erythematosus. "Overexpression of IFN-γ and calnexin in our study is suggestive of increased processing and endosomal trafficking of antigens and presentations to the cytotoxic T-lymphocytes that was reported to be involved in the pathogenesis of lupus nephritis." (PMID 27835693, 2016).
mastocytoma (1 paper, 2022). A localized tumor composed of sheets of mast cells without atypia. "It was described that the calnexin, a molecular chaperone in the ER, was expressed on the cell surface in various cells, such as mastocytoma cells, murine splenocytes, fibroblast cells, and human HeLa cells." (PMID 35237595, 2022).
myasthenia gravis (1 paper, 2020). Myasthenia gravis (MG) is a rare, clinically heterogeneous, autoimmune disorder of the neuromuscular junction characterized by fatigable weakness of voluntary muscles. "It was one of four susceptibility genes(PPP6R2, CANX, FAM136A,and FAM69A) (p < 0.05) in ophthalmoplegic subphenotypes of myasthenia gravis (OP-MG), showed altered expression." (PMID 32098576, 2020).
myositis (1 paper, 2018). "The biopsy specimens from patients with myositis also showed co-localization of MHC class I and the ER marker, calnexin." (PMID 29587702, 2018).
neuroectodermal tumour (1 paper, 2007). "The ER stress genes ERdj5, ERp57, GRP78, calreticulin and calnexin were induced in neuroectodermal tumour cells by fenretinide." (PMID 17353921, 2007).
oral cancer (1 paper, 2022). "Calnexin or CANX is an ER stress chaperone transmembrane protein involved in glycoprotein folding, is considered a prognostic indicator and therapeutic target in CRC, and is found to restrict antitumor CD4+ and CD8+ T cells in oral cancer." (PMID 36033825, 2022).
pancreatic cancer (1 paper, 2015). "In addition, we demonstrated that pancreatic cancer cells expressed high levels of genes belonging to the ER stress/UPR system including proximal signal sensors (PERK, ATF6 and ERN1), the chaperone lectins (Calnexin) and the folding catalysts (PDI)." (PMID 25657029, 2015).